TSPY9 (testis specific protein Y-linked 9)
Description:
May be involved in sperm differentiation and proliferation.
Synonyms: TSPY9P
Gene: Protein-coding gene on chromosome Y (9,487,267 to 9,490,081, forward strand). Ensembl gene ENSG00000238074.
Subcellular location: Cytoplasm; Nucleus
Subcellular location (Human Protein Atlas): Cytosol
Gene Ontology:
Biological process: nucleosome assembly
Cellular component: chromatin; cytoplasm; nucleus
Homologues: Orthologues: macaque TSPY2 (70% identical), zebrafish tspy (27% identical), Drosophila melanogaster Set (22% identical), Caenorhabditis elegans spr-2 (19% identical), Drosophila melanogaster Nap1 (14% identical), Caenorhabditis elegans nap-1 (14% identical), Drosophila melanogaster CG3708 (12% identical), Drosophila melanogaster mil (12% identical), zebrafish nap1l4a (12% identical). Paralogues in human: TSPY4 (99% identical), TSPY10 (98% identical), TSPY3 (98% identical), TSPY1 (97% identical), TSPY2 (97% identical), TSPY8 (97% identical), TSPYL1 (33% identical), TSPYL4 (31% identical), TSPYL5 (31% identical), TSPYL2 (30% identical), TSPYL6 (28% identical), SET (25% identical), and 6 more.